ABCG2 (ATP binding cassette subfamily G member 2 (JR blood group))
Diseases named in the same sentence as ABCG2 in open-access papers (continued):
Sharing a sentence is not in itself a finding about the gene and the disease.
cancer (continued). "Since then, the role of ABCG2 mRNA and protein overexpression in multidrug resistance has been well established in various cancer cell types." (PMID 37445716, 2023). "ABCG2 extrudes various compounds, including therapeutic agents and other endogenous or exogenous toxic substances, from cancer cells, contributing to multidrug resistance (MDR)." (PMID 37511298, 2023). "In cancer tissue, ABCG2 is responsible for the elimination of a variety of cytotoxic agents out of the cell, and the upregulated expression of this protein is associated with poor or failing response to chemotherapy." (PMID 38004447, 2023). "By contrast, the transcription activity of ABCG2, spheroid formation, clonogenicity, and the expression of cancer stem-like traits-related genes was respectively enhanced, and the sensitivity to oxaliplatin was attenuated, in CRC cells by WDR5 overexpression." (PMID 37708089, 2023). "Specifically, for a range of resistant cancer cells, the ATP-binding cassette efflux transporter G2 (ABCG2) is involved in drug efflux." (PMID 37990267, 2023). "Inhibition of EGFR also led to downregulation of PI3K, AKT, ERK and interestingly ABCG2, antiporter reported to facilitate development of cancer drug resistance." (PMID 35813479, 2022). "In cancer cells, the expression of ABCG2 is related to the presence of “side population” (SP) phenotype." (PMID 35631660, 2022). "Its treatment significantly sensitized ABCB1 or ABCG2 overexpressing cancer cells by impairing the functions of ABCB1 and ABCG2 in these transporter-amplified cancer cells." (PMID 35053461, 2022). "In this study, ABCG2 expression shows a positive correlation with the ImmuneScore and the StromalScore in most types of cancer." (PMID 36555598, 2022). "Licorice can also promote the apoptosis of some cancer cells, inhibit their growth and reproduction, and reverse the drug resistance of ABCG2-mediated drug-resistant cancer cells in a concentration-dependent manner." (PMID 35885926, 2022). "shRNA silencing of mortalin reduced cancer cell stemness by downregulating ABCG2, OCT-4, CD133, ALDH1, CD9, MRP1, and connexin expression levels, leading to a higher ability to form spheroids." (PMID 35859897, 2022). "ABCG2 expression was analyzed in 39 samples, the threshold value was 1% as ABCG2 expresses in cancer stem cells being the minor population." (PMID 35328603, 2022). "In this study, for the first time, a pan-cancer analysis of ABCG2 expression and its correlation with clinical prognosis, stemness score, tumor microenvironmental score, TMB, and MSI was performed, aiming to understand the role of ABCG2 in tumorigenesis." (PMID 36555598, 2022). "This pan-cancer study provides, for the first time, a comprehensive understanding of the multifunctionality of ABCG2 and unveils further details of the potential therapeutic role of ABCG2 in pan-cancer." (PMID 36555598, 2022). "Similar to its functional homologues ABCB1 and ABCC1, ABCG2 also has a notorious function in extruding antitumor drugs from various cancer cells, which can result in multidrug resistance, a severe obstacle in cancer treatment." (PMID 36294746, 2022). "The ability of ABCG2 to transport a wide range of conventional anticancer drugs and molecularly targeted agents contributes to poor clinical outcomes in cancer patients." (PMID 36361555, 2022). "Another member of the ABC superfamily with a well-acknowledged role in cancer resistance is ABCG2, better known as breast cancer resistance protein (BCRP)." (PMID 35629286, 2022). "Another inhibitor, dacomitinib, was shown to inhibit ABCG2 efflux pumps and enhance drug accumulation and retention, thereby reversing ABCG2-mediated MDR in cancer cells." (PMID 36153528, 2022). "Numerous natural products are known to be capable of reversing MDR in ABCB1- and ABCG2-overexpressing multidrug-resistant cancer cells." (PMID 36361555, 2022).
cancer (continued). "Cancer stem cells possess vast numbers of nuclear membrane transporters such as ABCG2 that can pump small chemicals like Hoechst dye out of the nuclei, thereby keeping them stain negative." (PMID 35404029, 2022). "Our findings identify that PFKFB3 is a novel target to regulate cancer stem cells and its associated therapeutic resistance markers YAP/TAZ and ABCG2 in SCLC models." (PMID 35804016, 2022). "A plethora of cancer-associated markers such as CD133, CD44, ABCG2, aldehyde dehydrogenase, octamer binding transcriptional factor 4, SOX2, and NANOG have been reported in cancer stem cells." (PMID 35992863, 2022). "The expression analysis via TIMER2.0 indicates that different cancers and specific cancer subtypes affect the ABCG2 gene expression status." (PMID 36555598, 2022). "For example, our previous studies show that these two cell lines have different surface expression levels of drug efflux pumps (MDR1 and ABCG2), as well as different levels of cancer stem cell surface markers (EpCAM and CD133)." (PMID 36358973, 2022). "We determined that high LEPRE1 levels induce protein kinase B activation, overexpression of ATP-binding cassette superfamily G member 2 (ABCG2) and E-cadherin, and cell colonization, resulting in a cancer stem cell-like phenotype." (PMID 35190588, 2022). "Expressions of cancer stem cell-related genes ABCG2, NANOG, ALDH1, OCT4, and SOX2 were significantly down-regulated in si-RSU1P2-1 and si-RSU1P2-2 groups compared to si-NC group (p < 0.05)." (PMID 35156514, 2022). "In this study, we investigated the modulatory effect of hydroxygenkwanin on ABCB1- and ABCG2-mediated MDR in multidrug-resistant cancer cells." (PMID 36361555, 2022). "It possesses potent cytotoxic properties toward a variety of cancer cell lines involving interaction with breast cancer resistance protein (ABCG2/BCRP) and antiangiogenesis." (PMID 35889493, 2022). "High ABCG2 expression in cancer cells results in resistance to a wide spectrum of chemotherapeutic agents, including mitoxantrone, topotecan, SN-38, and doxorubicin." (PMID 35163878, 2022). "Based on the results, ABCG2 was differentially expressed in tumors, of which a lower expression was found in most cancer types but a significantly higher expression in KIRC and LGG patients, which illustrated the flexible function of ABCG2 among pan-cancer." (PMID 36555598, 2022). "In fact, considering ABCG2 exports PpIX, the level of this transporter should be higher in normal cells than cancer cells in order to observe a higher fluorescence rise in the latter." (PMID 35887311, 2022). "Emerging evidence from research or clinical studies reported that ABCG2 (ATP-binding cassette sub-family G member 2) interrelates with multidrug resistance (MDR) development in cancers." (PMID 36555598, 2022). "The exposure of sensitive HCC cells to extracellular vesicles carrying linc-VLDLR increased ABCG2 expression, with a consequent reduction in cancer cell death." (PMID 35629286, 2022). "ABCG2 overexpression confers the side population phenotype, which is employed for quantifying the chemoresistant subpopulation in cancer cells." (PMID 35956408, 2022). "Studies have reported that the direct inhibition, and/or transient down-regulation, of ABCG2 are two of the most common mechanisms by which multidrug-resistant cancer cells become sensitized to cytotoxic anticancer drugs." (PMID 36361555, 2022). "ABCG2 is thought to be a marker of cancer stem cells (CSCs) in some cancers and is to blame for the side-population effect." (PMID 35897925, 2022). "ABCG2 (the second member of the ABCG subfamily) plays an intrinsic role in inducing MDR inside the cancer cells." (PMID 35224675, 2022). "ATP-binding cassette subfamily B member 1 (ABCB1) or P-glycoprotein (P-gp) and ATP-binding cassette subfamily G member 2 (ABCG2) play indispensable roles in cancer cell MDR." (PMID 36120340, 2022).
cancer (continued). "In the frame of chemoresistance related to extracellular vesicles, some reports indicated regulation of ABCG2 expression by long noncoding RNAs and circular RNA present in exosomes released by cancer cells." (PMID 35629286, 2022). "The ABC family members ABCB1, ABCC1, and ABCG2, which are related to drug resistance in several types of cancer, were first evaluated in MDA-MB-231 cells." (PMID 36291159, 2022). "In the context of drug resistance in cancer cells, ABCG2 has the feature of extruding a wide spectrum of chemically unrelated chemotherapeutic drugs, such as mitoxantrone, camptothecins, and tyrosine kinase inhibitors (TKIs)." (PMID 36614168, 2022). "Following those phenotypes, it has been described that the expression of stem cell transcription factors, such as CD44, SOX2, CD133 ABCG2, and Nanog, play a pivotal role in determining the aggressiveness of cancer." (PMID 35884836, 2022). "Overexpression of breast cancer resistance transporter (BCRP/ABCG2) in cancers has been explained for the failure of chemotherapy in clinic." (PMID 36362047, 2022). "ABCC4 and ABCG2 have the function of excreting UA in the kidney and serve as substrates for the transport of various anti-cancer drugs and environmental carcinogens in various organs." (PMID 36302802, 2022). "We found that ABCG2-mediated drug efflux in ABCG2-overexpressing cancer cells and ABCG2-transfected HEK293 cells was strongly inhibited by hydroxygenkwanin." (PMID 36361555, 2022). "Breast cancer-resistance protein/ATP-binding cassette super-family G member-2 (BCRP/ABCG-2) is a transporter protein which can remove host of toxic substances from cell comprising Qu, a different flavonoid which have promising future in cancer treatment." (PMID 36557997, 2022). "We divided the cancer types into high-expression and low-expression groups according to the expression levels of ABCG2 and investigated the correlation of ABCG2 expression with the prognosis of patients within different tumors." (PMID 36555598, 2022). "In cancer therapy, inhibition of ABCG2 has emerged as a new treatment strategy that is believed to increase chemotherapeutic drug bioavailability and to overcome drug resistance." (PMID 36555598, 2022). "In this work, we investigated the interaction of ensartinib with P-glycoprotein (P-gp) and ABCG2, two ATP-binding cassette (ABC) multidrug efflux transporters that are commonly associated with the development of multidrug resistance in cancer cells." (PMID 35565470, 2022). "RNA sequencing of cancer cells in this study revealed ABCB1 and ABCG2 to associate with resistance to topoisomerase inhibitors." (PMID 35719112, 2022). "Rivoceranib, a potent inhibitor of vascular endothelial growth factor receptor 2 (VEGFR-2), has been shown to reverse ABCB1- and ABCG2-mediated resistance in cancer cells." (PMID 35327403, 2022). "We discovered that, in a concentration-dependent manner, hydroxygenkwanin significantly reverses ABCG2-mediated resistance to multiple cytotoxic anticancer drugs in ABCG2-overexpressing multidrug-resistant cancer cells." (PMID 36361555, 2022). "In contrast, in ABCG2 high expressing cancer tissues, ABCG2 contributes to drug resistance in cancer treatments." (PMID 36555598, 2022). "We observed that following treatment mRNA levels of ABCG2 were reduced significantly when comparing both cancer cell lines to control." (PMID 35118633, 2022). "The corresponding heatmap data among pan-cancer show a positive correlation between ABCG2 and EPAS1, and GCLC in most cancer types." (PMID 36555598, 2022). "Exposure to exogenous TGF-β1 resulted in a reduction in mRNA expression of ABCG2 compared to controls which was significant between control and treated cancer cell lines." (PMID 35118633, 2022).
cancer (continued). "As it was noted in the previous section, the overexpression of ATP-dependent efflux pumps, such as ABCB1, ABCB4 and ABCG2, is a common phenomenon in drug-resistant cancers and these genes were included in the “response to drug’’ process in our data." (PMID 36078127, 2022). "ABCG2 is a well-known marker of cancer stem-like cells and contributes to the resistance of these cells to chemotherapy." (PMID 35631574, 2022). "In an in vitro experiment, inhibition of SMAD3 C-terminal phosphorylation reversed ABCB1- and ABCG2-mediated multidrug resistance in cancer cell lines, E4BP4-mediated NK cell development, and tumor metastasis." (PMID 35085106, 2022). "The breast cancer resistance protein (BCRP or ABCG2) involved in cancer multidrug resistance (MDR), transports many hydrophobic compounds, including a number of anti-cancer drugs." (PMID 35053477, 2022). "Among 49 identified members, P-glycoprotein (ABCB1), breast cancer resistance protein (ABCG2) and MDR-associated protein 1 (ABCC1) have been well-clarified to play critical roles in the promoting MDR phenomenon in cancer." (PMID 36559089, 2022). "ABCG2 correlates with drug resistance in several types of cancer possibly due to its expression in CSCs." (PMID 36555598, 2022). "Of the selected ABC transporters, ABCG2 is also a known cancer stem cell marker in PCa and was analyzed in more detail." (PMID 36614114, 2022). "Several studies have revealed that ABCG2 as a biomarker of cancer stem-like cell (CSC) populations can limit the efficacy of chemotherapy and is a target for clinical interventions during the period of tumor relapse." (PMID 36555598, 2022). "The most significantly enriched signal transduction pathways were selected, and six types of cancers show the strongest potential connection with the ABCG2 gene expression." (PMID 36555598, 2022). "Among the ABC transporter superfamily, P-glycoprotein (P-gp/ABCB1), multidrug resistance protein 1 (MRP1/ABCC1), and breast cancer resistance protein (BCRP/ABCG2) are considered to be the most closely related to MDR in cancer cells." (PMID 35565231, 2022). "ABCG2 contributes to chemoresistance through the efflux of anticancer drugs from cancer cells and MYCN was shown to be positive regulator of ABCG2." (PMID 35996085, 2022). "ABCG2 also endows cancer cells with pluripotency, higher proliferation rates, and induced tumorigenicity." (PMID 36474162, 2022). "It has also been shown that c-Met/PI3K/Akt signaling is responsible for resistance to photodynamic therapy and doxorubicin in carcinomas via enhancement of BCRP/ABCG2 expression." (PMID 35986321, 2022). "In particular, we assessed the antitumor efficacy of OTS964 in the presence of ABCG2 in cancer cells." (PMID 33658942, 2021). "Our data indicated that TP-3654 reverses ABCG2-mediated MDR and increased apoptosis of ABCG2-overexpressing cancer cells by inhibiting the drug transport function of ABCG2." (PMID 34502348, 2021). "ABCG2 is a multidrug transporter that affects drug pharmacokinetics and contributes to multidrug resistance of cancer cells." (PMID 34282134, 2021). "ABC family members including ABCB1, ABCC1, ABCC2, ABCC3, and ABCG2 were critical for CDDP resistance of cancer cells." (PMID 33754002, 2021). "Both ABCG2-overexpressing cancer cells NCI-H460/TPT10 and S1-M1-80 were significantly insensitive to MLN7243, and S1-M1-80 cells showed more than 1,000-fold resistance to MLN7243." (PMID 34336849, 2021). "Specifically, the expressions of PEPT1 and ABCB6 were upregulated in dormant cancer cells, whereas that of ABCG2 was downregulated." (PMID 33790399, 2021). "Cancer stem cells are known to express elevated levels of ABCG2 and consequently are characterized with multi-drug chemoresistance." (PMID 34884848, 2021). "The abnormal expression of the transcription factors Gli1 and Gli2 in the Hh signaling pathway regulates the expression of ABCG2 in many cancers." (PMID 34659526, 2021).
cancer (continued). "ABC transporters including ABCB1, ABCC1, ABCC2, and ABCG2 are involved in the reduction of chemosensitivity in cancer cells." (PMID 34066059, 2021). "ABCG2 expression mainly identifies fast-cycling tumor progenitors, and the ABCG2- population contains primitive stem-like cancer cells in the SP fraction." (PMID 33589595, 2021). "Several aptamers, available against CSC markers (CD44, CD133, ABCG2, etc.), can be used as a bait to trap cancer stem cells from a heterogeneous population." (PMID 34575825, 2021). "Recent studies have shown that tanshinone IA exhibits MDR reversing potential to human ER-negative breast cancer cells by downregulating BCRP/ABCG2 expression in cancer cells." (PMID 35145409, 2021). "In cancer patients, a combination of GS-9973 and ABCG2 substrate drugs is a beneficial treatment option for cells with high ABCG2 expression." (PMID 34326700, 2021). "The parental cancer cells, H460, and the cell line overexpressing ABCG2, H460MX20, were treated with SN-38 in the absence or presence of inhibitors." (PMID 33469044, 2021). "In the present study, we report that RUNX1 acts as an oncogene in CRC by activating the Hedgehog signaling pathway to promote cancer cell proliferation and regulating ABCG2 expression to reduce the sensitivity of cancer chemotherapy." (PMID 34659526, 2021). "The treatment of NCI-H460/MX20 cancer cells with 3 μM of GS-9973 for 72 h significantly inhibited the ABCG2 protein expression level compared to the untreated cells." (PMID 34326700, 2021). "Although the expression of ABCG2-Q141K in cancer cells resulted in elevated sensitivity to imatinib, the in vivo effect of Q141K on imatinib accumulation/response is controversial." (PMID 33801813, 2021). "Licochalcone A suppressed ABCG2-mediated resistance and restored the chemosensitivity of cancer cells to mitoxantrone and topotecan, a well-known ABCG2 substrates." (PMID 34073042, 2021). "Several studies have established that cancer stem-like cell (CSC) population in cancer expressing ABCG2 limits the efficacy of chemotherapy and is responsible for the re-emergence of tumors during the period of relapse in various cancer patients 34-36." (PMID 34326700, 2021). "Of note, ABCG2 transports anti-cancer agents such as irinotecan, 7-ethyl-10-hydroxycamptothecin (SN-38), gefitinib, Imatinib, methotrexate, and mitoxantrone from cells." (PMID 33562088, 2021). "Previous in vitro studies from our lab have shown some of the selective TKIs can sensitize ABCG2-mediated cancer resistance in various cancer scenarios 44-46." (PMID 34326700, 2021). "One of the most probable explanations for reduced drug efficacy in ABCB1- and ABCG2-overexpressing multidrug-resistant cancer cells is the reduced intracellular drug accumulation caused by ABCB1- and ABCG2-mediated drug efflux." (PMID 33807514, 2021). "Except for P-gp, ABCC1(also known as MRP1)and ABCG2 (also known as BCRP) have also been extensively studied, confirming their prominent roles in multidrug resistance of cancer cells." (PMID 33953682, 2021). "Our results here confirmed that TP-3654 resensitized ABCG2-overexpressing cancer cells to ABCG2 substrate drug by enhancing drug-induced apoptosis, and not by initiating growth retardation." (PMID 34502348, 2021). "ABC transporters, in particular ABCB1 and especially ABCG2, are abundantly expressed in hematopoietic progenitor cells and are overexpressed in cancer and CML stem cells." (PMID 34055641, 2021). "Considerable efforts have been directed at developing specific inhibitors of ABCG2 to counteract its activity in protecting tumor cells from anti-cancer drugs." (PMID 34282134, 2021). "Six of these genes were not expressed or were very weakly expressed (ABCC11, SLC22A6, SLC22A7, SLC22A8, SLC22A9, SLCO1B1), and among the other eight genes, only gene ABCG2 showed significant difference in expression in cancer versus adjacent control tissue." (PMID 33917029, 2021).